NGF (nerve growth factor)
Diseases named in the same sentence as NGF in open-access papers (continued):
Sharing a sentence is not in itself a finding about the gene and the disease.
depression (continued). "While there is strong evidence linking BDNF to stress and depression, other neuronal growth factors are also involved, most notably glial cell-line derived neurotrophic factor (GDNF) and nerve growth factor (NGF; Hayley and Litteljohn, 2013)." (PMID 24723864, 2014). "The upregulation of NGF, BDNF, GDNF, and other neurotrophic factors is considered for treatment of depression and neurodegenerative diseases." (PMID 23878590, 2013). "However some data obtained in rodent models of depression indicates that NGF has significant antidepressant effects, and that NGF levels are decreased, suggesting this neurotrophin might also play a role in the events leading to depression." (PMID 22654714, 2011). "Elevated NGF levels are observed under certain circumstances, e.g., sertraline treatment of patients with mild and moderate depression without somatic syndrome." (PMID 40783715, 2025). "The vagal parasympathetic stimulation by SMT, could then release neurotrophins (brain-derived neurotrophic factor, BNDF and nerve growth factor, NGF) to help resolve depression and related neuro-cognitive impairments." (PMID 38555403, 2024). "Our data revealed that MGO-induced depression like-behavior and memory deficits resulted from disturbances in Trp, 5-HT, BDNF, and NGF levels, increased p-Tau and APP expression, neuroinflammation, and impaired redox status (Nrf-2/Ho-1/TXNRD1/Sirt3/5) in the brain." (PMID 39574138, 2024). "Our study reveals that a single latent vector can be extracted from data pertaining to NGF, ROI, and the depression phenotype, and that 59.5% of the variance in this ROI-NGF-pathway phenotype may be explained by ACEs." (PMID 37509019, 2023). "Lower NGF levels have also been observed in the hippocampus in some animal models of depression, but not in the Flinders Sensitive Line rat model." (PMID 37509019, 2023). "We found that one validated and replicable latent vector could be extracted from NGF, ROI, and the depression phenome, which therefore constitutes a novel ROI-NGF-pathway-phenotype." (PMID 37509019, 2023). "Before conducting PLS analysis, we examined whether one PC could be extracted from NGF data and the ROI and depression PC_phenome scores." (PMID 37509019, 2023). "NGF and BDNF are two members of the neurotrophic factor family with crucial roles in the formation and plasticity of cerebral neural networks, and they are mainly involved in the pathophysiological mechanism of depression." (PMID 37298063, 2023). "Indeed, we showed here that the expression of neurotrophic factors, such as BDNF, NGF, and FGF-2, which are negatively affected in the pathogenesis of depressive disorders, can be enhanced by short-term treatment with irisin." (PMID 37298063, 2023). "Various NTs, including BDNF, NGF, and GDNF, as well as their receptors can also be upregulated by lithium, a metal with a long-lasting history of use as first-line drug for treating bipolar disorder and depression." (PMID 35892326, 2022). "Another study of depression in adolescent patients discovered increased BDNF but no changes in NGF or GDNF." (PMID 35431783, 2022). "Moreover, it has been described that BDNF, NT3 and NGF neurotrophins are involved in BPSD, such as anxiety, depression and aggressive behaviour." (PMID 36010679, 2022). "Furthermore, a study found that supplements with probiotics ameliorated the depression-like behaviors of rats with epilepsy through upregulating the expression levels of BDNF and nerve growth factor." (PMID 36358502, 2022). "Vitamin D3 also strengthens the nerve growth factor (NGF) and glial derived neurotrophic factor (GDNF), and GDNF may have a role in depression." (PMID 34473420, 2021). "GDNF and NGF were significantly downregulated in the hippocampus and PFC, which might contribute to increase the anxiety and depression levels in the offspring from IVF-ET and IVF-FET groups." (PMID 34605773, 2021).
depression (continued). "While the available antidepressants such as fluoxetine and venlafaxine are known to elevate the levels of NGF and BDNF both in the serum of depression patients and in depression-like animal models, the long-term use of these antidepressants can cause many side effects." (PMID 33364963, 2020). "Furthermore, σ1R upregulates neurotrophic factors such as brain-derived neurotrophic factor (BDNF) and nerve growth factor (NGF), proteins whose regulation and expression seem to be involved in the pathophysiology of depression." (PMID 29903051, 2019). "One may retort that even depression is very common among old patients with chronic diseases, and that several studies report reduced level of both BDNF and NGF serum levels in major depressive disorder which contrast our results." (PMID 28068360, 2017). "Interestingly, nerve growth factor (NGF) and calcitonin gene–related peptide (CGRP) have been reported as relevant factors for depression." (PMID 29149884, 2017). "Based on these data, KXS might enhance the expressions of NGF and BDNF via regulating tPA system in stimulating synthesis of mNGF, which might account for its anti-depression effect." (PMID 28469194, 2017). "The role of proNGF/mature NGF in etiology of depression disorder is not sufficient to be studied compared with that in AD35." (PMID 28469194, 2017). "Indeed, NGF content was elevated 6 h after training of rats in the LH paradigm, and CNTF knock-out mice were more prone to depression-like behavior in the LH model." (PMID 24999483, 2014). "Reduced NGF and BDNF signaling in the adult brain may be involved in the pathophysiology of psychiatric disorders, such as depression, and a role for NGF has been proposed in the etiopathogenesis of schizophrenia." (PMID 22474604, 2012). "Therefore, we hypothesized that the potential mechanism of miR-182-5p involved in regulating depression might be mediated by targeting the expression level of BDNF, NF-α1, or nerve growth factor." (PMID 38038373, 2024). "Very little is known about the serum NGF and proNGF in humans, while the serum BDNF and proBDNF ratio has been investigated—, also the relationship to the psycho-cognitive parameters, in patients with major depression, obstructive sleep apnea with psoriasis, and autism." (PMID 37175781, 2023). "In short, Geum japonicum, garlic essential oil, fish oil, conjugated linoleic acid, and anthocyanin could ameliorate depression through increasing the production of BDNF, nerve growth factor, and neurotrophin-3, and their effects and mechanisms should be further investigated by clinical trials." (PMID 36358502, 2022). "The studies also do not find whether there is a significant difference between the level of nerve growth factor in the serum of patients with depression without and with suicidal thoughts." (PMID 33804468, 2021). "There was a clear baseline difference of plasma BDNF levels, NGF levels, NT-3 levels, and NT-4 levels between the depression group and the nondepression group; however, the pro-BDNF plasma levels were not significantly different between these two groups (p = 0.830, d = −0.05)." (PMID 32210759, 2020). "Since the analysis of the set of basic genes associated with the neurotrophic theory of depression did not provide any conclusive feedback, the next step was to determine the expression of three neurotrophic factors, BDNF, NGF, and NTF3, on the protein level assessed by Western blot." (PMID 30294251, 2018). "The reason for the variation of the pain is unknown, although it seems the modulation of the proposed central pain amplification may be mediated by NMDA receptors and nerve growth factor (NGF), as well as cognitive and emotional comorbidities such as depression." (PMID 24575066, 2014).
depression (continued). "Unlike BDNF, NGF, and FGF-2, which were reduced in association with depression, plasma levels of VEGF were elevated or unchanged in drug-free patients with an acute episode of major depression and VEGF levels were unrelated to depression scores." (PMID 23675319, 2013). "Interestingly, Beck’s depression inventory (BDI)-II showed negative correlation with ß-NGF levels." (PMID 38362105, 2024). "Hence, the present study was carried out to examine: (a) NGF, SCF, SCGF, HGF and M-CSF, in relation to VEGF, PDGF and FGF, and the neurotoxicity immune profile in MDD; and (b) whether NGF or the other growth factors mediate the effects of ACEs and ROI on the depression phenome." (PMID 37509019, 2023). "Molecular and behavioral studies deepened the role of neurotrophic/growth factors (such as BDNF, NGF, IGF-1, and FGF-2) in depression, demonstrating that the levels of those factors were reduced in animal models and in depressed and/or stressed patients (“neurotrophic hypothesis of depression”)." (PMID 35886944, 2022). "Other neurotrophins, including nerve growth factor (NGF), glia cell-derived neurotrophic factor (GDNF), and neurotrophin-3 (NT-3), are also important factors for regulation of neuroplasty and were implied to play a role in the neurotrophic hypothesis of depression." (PMID 25477997, 2014). "Our study showed that overall BDNF, NGF, NT-3, and NT-4 levels are higher in METH users with depression compared to METH addicts without depression (d = 0.65, 0.59, 0.76, 0.78, respectively)." (PMID 32210759, 2020). "Such a serum NGF/BDNF balance is not observed normally nor in psychological stress, depression, autoimmune diseases or acute coronary syndrome." (PMID 21085492, 2010). "Interestingly, Beck’s depression inventory (BDI)-II, as depression parameter, showed negative correlation with ß-NGF levels." (PMID 38362105, 2024). "However, some studies have shown that serum levels of GDNF, NGF, and NTF3 in patients with major depression are not significantly different." (PMID 37509026, 2023). "One explanation for the reduced levels of both neurotrophins (NGF and BDNF) in our study could be that a subgroup of the EM and CM patients had concomitant undiagnosed depression and therefore were not receiving antidepressants." (PMID 34991456, 2022). "Unlike NGF and BDNF, there are not many studies currently examining NT-3 and NT-4/5 in depression." (PMID 34393735, 2021). "Nevertheless, the relationship between regular physical activity, cognitive factors (plasma nerve growth factor (NGF), brain-derived neurotrophic factor (BDNF), and cathepsin B levels), and psychological parameters (the climacterium, depression, and cognition) has not yet been investigated." (PMID 33233633, 2020). "In addition to the decreased contents and expression of BDNF and its cognate TrkB receptor, the levels of nerve growth factor (NGF) and its receptor TrkA proteins and mRNAs are also lower in the hippocampus of suicide victims with major depression as compared to nonpsychiatric individuals." (PMID 24999483, 2014).
osteoarthritis (113 papers, 2008 to 2026). A noninflammatory degenerative joint disease occurring chiefly in older persons, characterized by degeneration of the articular cartilage, hypertrophy of bone at the margins and changes in the synovial membrane. "Nerve growth factor (NGF) is a neurotrophic factor directly associated with inflammatory and autoimmune diseases like osteoarthritis, multiple sclerosis, and rheumatoid arthritis." (PMID 38612839, 2024). "In particular, the use of the new drug tanezumab (NGF antibody) has been found to cause rapidly progressive osteoarthritis, which requires immediate joint replacement treatment in severe cases." (PMID 39075502, 2024). "CGRP and NGF are sensory neuropeptides and proinflammatory biomarkers that are associated with pain transmission and modulation in osteoarthritis (OA)." (PMID 39553645, 2024). "Monoclonal anti‐NGF antibody treatment has been shown to attenuate osteoarthritis‐associated pain in humans, dogs, and cats." (PMID 37083137, 2023). "Serum NGF concentration was high in the cohort with advanced osteoarthritis and should be investigated as a marker for osteoarthritis‐associated pain." (PMID 37083137, 2023). "Our results show that, on a group level, serum NGF concentration is increased in horses with lameness associated with advanced osteoarthritis compared with sound horses and horses with milder disease." (PMID 37083137, 2023). "Our aim was to quantify serum NGF concentrations in horses with lameness associated with advanced osteoarthritis and compare these to serum concentrations in horses with milder disease and in young healthy (sound) horses." (PMID 37083137, 2023). "Based on these findings, serum NGF concentration should be investigated as a marker for osteoarthritis‐associated pain." (PMID 37083137, 2023). "Because NGF concentration has been determined to increase in both of these processes, it likely plays a central role in osteoarthritis‐associated pain." (PMID 37083137, 2023). "Quantify and compare serum NGF concentration in horses with osteoarthritis‐associated lameness and sound horses." (PMID 37083137, 2023). "NGF/TrkA signaling elevates synovial sensory neuronal distributions in the joints and causes osteoarthritis (OA) pain." (PMID 36292950, 2022). "NGF antagonists require in-depth assessment of risk–benefit ratios before using in patients with osteoarthritis." (PMID 33987515, 2020). "For example, a critical role for NGF in damaged tissues has been linked to mechanically evoked pain in osteoarthritis, and this pain can be reversed in man by the application of neutralising anti-NGF monoclonal antibodies." (PMID 24846747, 2015). "Nerve growth factor (NGF) level is increased in osteoarthritis (OA) joints and is involved in pain associated with OA." (PMID 24438745, 2014). "The clinical efficacy of anti-human NGF mAbs has been demonstrated in several human studies including several large-scale phase 3 clinical trials: responses to the pain associated with osteoarthritis (OA), lower back pain and cystitis have been evaluated." (PMID 24206926, 2013). "Anti-NGF monoclonal antibodies have demonstrated analgesic activity in osteoarthritis but are associated with joint-specific safety signals, including increased rates of rapidly progressive osteoarthritis in phase III trials." (PMID 41567220, 2025). "This targeted binding allows anti-NGF antibodies to reduce pain and inflammation while minimizing the risk of autoimmune complications for conditions associated with excessive pain, such as osteoarthritis and rheumatoid arthritis." (PMID 37998739, 2023). "Serum NGF concentration should be evaluated in horses with osteoarthritis‐associated lameness." (PMID 37083137, 2023). "Because the inhibition of NGF can be used to treat osteoarthritis‐associated chronic pain, measurement of NGF may be useful in detecting such pain." (PMID 37083137, 2023).
osteoarthritis (continued). "Moreover, a complete loss of pain perception is not necessarily helpful and treatment with anti-NGF medications can cause an increase in osteoarthritis pathology that caused an initial halting of anti-NGF therapies." (PMID 31920521, 2019). "On December 23, 2010, the FDA placed ongoing fulranumab studies on clinical hold because of a concern that the entire class of anti-NGF antibodies may be associated with a condition representing either rapidly progressing osteoarthritis or osteonecrosis." (PMID 28056917, 2017). "Several pro-inflammatory mediators may be recruited into the osteoarthritis joint associated with damage, including nerve growth factor (NGF), nitric oxide (NO) and prostanoids." (PMID 23905081, 2013). "On December 23, 2010, the United States Food and Drug Administration (FDA) placed ongoing fulranumab studies on clinical hold because of a concern that the entire class of anti-NGF antibodies may be associated with a condition representing either rapidly progressing osteoarthritis or osteonecrosis." (PMID 28056917, 2017). "Anti-NGF monoclonal antibodies have recently been approved for treating degenerative joint disease, including osteoarthritis pain, in dogs and cats." (PMID 41608074, 2026). "Nexvet successfully converted the rat anti-NGF mAb (αD11) into caninized and felinized anti-NGF mAbs, aimed at treating painful conditions, including osteoarthritis (OA), in dogs and cats (see Section 5.2)." (PMID 40002954, 2025). "NGF is upregulated in osteoarthritis, enhancing signaling via Tropomyosin receptor kinase A (TrkA) and promoting central sensitization." (PMID 41012116, 2025). "This was evidenced in 2012, when clinical trials of anti-NGF mAbs (aNGFmAbs) revealed rapidly progressive osteoarthritis (RPOA), leading the FDA to impose a two-year clinical trial hold and mandate a risk evaluation and mitigation strategy (REMS) post-hold." (PMID 40417367, 2025). "While bedinvetmab represents an innovative approach to canine osteoarthritis management through NGF inhibition, the potential for rapid joint degradation and other serious events warrants significant caution." (PMID 40740305, 2025). "That same year, a study was published investigating the effect of the anti-NGF mAbs bedinvetmab and frunevetmab on the quality of life of dogs and cats with osteoarthritis." (PMID 41301953, 2025). "In conditions such as osteoarthritis or fractures, inflammatory cells and damaged bone tissue release large amounts of NGF, exacerbating pain." (PMID 40860871, 2025). "Small-molecule NGF/pro-NGF inhibitors are also under pre-clinical investigation for their ability to disrupt NGF/proNGF binding to TrkA and p75NTR in the context of osteoarthritis." (PMID 40429806, 2025). "Anti-NGF monoclonal antibodies, developed for the management of osteoarthritis pain, have demonstrated clinical efficacy and good tolerability in several animal species, particularly dogs and cats." (PMID 41301953, 2025). "Elevated NGF levels are observed in chronic pain states (e.g., osteoarthritis, intervertebral disk degeneration), and in humans, an anti-NGF antibody (tanezumab) produced significant analgesia in clinical trials of osteoarthritis and chronic back pain." (PMID 41012116, 2025). "Neutralizing NGF with mAbs can significantly reduce pain in some osteoarthritis and low-back pain patients." (PMID 41012116, 2025). "While no peer-reviewed studies of an SP vaccine in animals have been reported to date, a search of the patent literature reveals a promising bivalent vaccine targeting both NGF and SP that has been tested in dogs with naturally occurring osteoarthritis." (PMID 41012116, 2025). "Monoclonal antibodies targeting nerve growth factor (NGF), such as tanezumab, have demonstrated significant efficacy in reducing pain associated with osteoarthritis and chronic lower back pain." (PMID 40230768, 2025).